PML (PML nuclear body scaffold)
Description:
Functions via its association with PML-nuclear bodies (PML-NBs) in a wide range of important cellular processes, including tumor suppression, transcriptional regulation, apoptosis, senescence, DNA damage response, and viral defense mechanisms. Acts as the scaffold of PML-NBs allowing other proteins to shuttle in and out, a process which is regulated by SUMO-mediated modifications and interactions. Inhibits EIF4E-mediated mRNA nuclear export by reducing EIF4E affinity for the 5' 7-methylguanosine (m7G) cap of target mRNAs. Isoform PML-4 also: acts as a transcriptional repressor of TBX2 during cellular senescence and the repression is dependent on a functional RBL2/E2F4 repressor complex, regulates double-strand break repair in gamma-irradiation-induced DNA damage responses via its interaction with WRN, acts as a negative regulator of telomerase by interacting with TERT, and regulates PER2 nuclear localization and circadian function. Isoform PML-6 inhibits specifically the activity of the tetrameric form of PKM. The nuclear isoforms (isoform PML-1, isoform PML-2, isoform PML-3, isoform PML-4 and isoform PML-5) in concert with SATB1 are involved in local chromatin-loop remodeling and gene expression regulation at the MHC-I locus. Isoform PML-2 is required for efficient IFN-gamma induced MHC II gene transcription via regulation of CIITA. Cytoplasmic PML is involved in the regulation of the TGF-beta signaling pathway. PML also regulates transcription activity of ELF4 and can act as an important mediator for TNF- and IFN-alpha-mediated inhibition of endothelial cell network formation and migration. Exhibits antiviral activity against both DNA and RNA viruses. Isoform PML-4 restricts varicella zoster virus (VZV) via sequestration of virion capsids in PML-NBs thereby preventing their nuclear egress and inhibiting formation of infectious virus particles. The sumoylated isoform PML-4 restricts rabies virus by inhibiting viral mRNA and protein synthesis. The cytoplasmic isoform PML-14 can restrict herpes simplex virus-1 (HHV-1) replication by sequestering the viral E3 ubiquitin-protein ligase ICP0 in the cytoplasm. Isoform PML-6 shows restriction activity towards human cytomegalovirus (HHV-5) and influenza A virus strains PR8(H1N1) and ST364(H3N2). Sumoylated isoform PML-4 and isoform PML-12 show antiviral activity against encephalomyocarditis virus (EMCV) by promoting nuclear sequestration of viral polymerase (P3D-POL) within PML NBs. Isoform PML-3 represses human foamy virus (HFV) transcription by complexing the HFV transactivator, bel1/tas, preventing its binding to viral DNA. PML may positively regulate infectious hepatitis C viral (HCV) production and isoform PML-2 may enhance adenovirus transcription. Functions as an E3 SUMO-protein ligase that sumoylates (HHV-5) immediate early protein IE1, thereby participating in the antiviral response. Isoforms PML-3 and PML-6 display the highest levels of sumoylation activity.
Synonyms: TRIM19; MYL; PP8675; RNF71
Tractability: Antibody: UniProt places it where antibodies can reach, with medium confidence. PROTAC: UniProt records ubiquitination sites on it; ubiquitination databases record sites on it; its protein half-life has been measured.
Target class: Enzyme; Transferase
Gene: Protein-coding gene on chromosome 15 (73,994,673 to 74,047,827, forward strand). Ensembl gene ENSG00000140464.
Subcellular location: Nucleus; Nucleus, nucleoplasm; Cytoplasm; Nucleus, PML body; Nucleus, nucleolus; Endoplasmic reticulum membrane; Early endosome membrane
Subcellular location (Human Protein Atlas): Nuclear bodies
Pathways (Reactome):
Disease: Dengue virus activates/modulates innate and adaptive immune responses; HCMV Early Events
Gene expression (Transcription): Regulation of RUNX1 Expression and Activity
Metabolism of proteins: SUMOylation of DNA damage response and repair proteins; SUMOylation of ubiquitinylation proteins
Developmental Biology: Transcriptional regulation of granulopoiesis
Immune System: Interferon gamma signaling
Signal Transduction: Regulation of PTEN localization
Gene Ontology:
Molecular function: molecular adaptor activity; protein binding; protein homodimerization activity; SUMO binding; SUMO transferase activity; ubiquitin protein ligase binding; ubiquitin-like protein ligase activity; metal ion binding; SMAD binding; zinc ion binding
Biological process: antiviral innate immune response; cellular senescence; maintenance of protein location in nucleus; negative regulation of angiogenesis; negative regulation of cell growth; negative regulation of cell population proliferation; negative regulation of DNA-templated transcription; negative regulation of ubiquitin-dependent protein catabolic process; PML body organization; positive regulation of extrinsic apoptotic signaling pathway; positive regulation of telomere maintenance; proteasome-mediated ubiquitin-dependent protein catabolic process; protein-containing complex assembly; regulation of DNA-templated transcription; regulation of double-strand break repair; response to cytokine; response to hypoxia; suppression of viral release by host; circadian regulation of gene expression; endoplasmic reticulum calcium ion homeostasis; entrainment of circadian clock by photoperiod; innate immune response; intrinsic apoptotic signaling pathway in response to DNA damage; and 15 more
Cellular component: chromosome, telomeric region; cytoplasm; nuclear body; nucleolus; nucleoplasm; nucleus; PML body; cytosol; early endosome membrane; endoplasmic reticulum membrane; nuclear matrix
Genetic constraint (gnomAD): Loss-of-function variants: 28 observed, 62.6 expected, observed/expected ratio (o/e) 0.45, 90% interval 0.33 to 0.61. The upper end of that interval is the gene's LOEUF score, 0.61, which puts it in group 2 of 6, group 1 being the genes least tolerant of losing a copy. Missense variants: 1,019 observed, 1,205.5 expected, observed/expected ratio (o/e) 0.85, 90% interval 0.8 to 0.89. Synonymous variants: 500 observed, 512.43 expected, observed/expected ratio (o/e) 0.98, 90% interval 0.91 to 1.05.
Homologues: Orthologues: macaque PML (95% identical), chimpanzee PML (94% identical), dog PML (78% identical), pig PML (73% identical), guinea pig PML (70% identical), rat Pml (69% identical), rabbit PML (69% identical), mouse Pml (67% identical). Paralogues in human: MID2 (14% identical), MID1 (14% identical), TRIM72 (13% identical), TRIM25 (12% identical), TRIM42 (12% identical), TRIM24 (12% identical), TRIM50 (11% identical), TRIM47 (11% identical), TRIM66 (11% identical), TRIM2 (11% identical), TRIM26 (11% identical), TRIM11 (11% identical), and 68 more.
Diseases named in the same sentence as PML in open-access papers:
PML is named in the same sentence as 214 diseases in open-access papers, as found by Europe PMC text mining. Sharing a sentence is not in itself a finding about the gene and the disease. The quoted sentences say what the papers report.
acute promyelocytic leukemia (719 papers, 2005 to 2026). An aggressive form of acute myeloid leukemia (AML), characterized by arrest of leukocyte differentiation at the promyelocyte stage, due to a specific chromosomal translocation t(15;17) in myeloid cells. "It has been proposed that the synergy of ATRA and ATO reverses the characteristic disorganization of promyelocytic leukemia (PML) bodies, as also observed in all types of NPM1-mutated AML, apart from APL." (PMID 40647396, 2025). "Beyond conventional JAK inhibitors, clinically validated small-molecule inhibitors targeting PML, such as Arsenic Trioxide (used successfully in acute promyelocytic leukemia), warrant investigation for CD-associated fibrosis." (PMID 40661957, 2025). "A prototypical example is acute promyelocytic leukemia, which is caused by the PML–RARα fusion gene, a product of the recombination between the promyelocytic leukemia (PML) gene and the retinoic acid receptor-α (RARα) gene." (PMID 40819127, 2025). "Promyelocytic leukemia nuclear bodies (PML-NBs) are nuclear structures associated with transcriptional regulation, viral infection response, genomic stability, apoptosis induction, and tumor suppression." (PMID 41154590, 2025). "SUMO5, the latest addition to the SUMO family, is associated with the assembly and disassembly of promyelocytic leukemia nuclear bodies (PML-NBs)." (PMID 40724953, 2025). "This idea is consistent with the function of PML-NBs in the genome (e.g., transcription, silencing, stemness, senescence), and the differentiation arrest of PML-mutated promyelocytic leukemias." (PMID 38066546, 2023). "The t (q24;q21), generating the chimeric fusion gene PML-retinoic acid receptor a (PML-RARa), is the hallmark of acute promyelocytic leukemia (APL)." (PMID 37124518, 2023). "The PML::RARA fusion protein is the hallmark driver of Acute Promyelocytic Leukemia (APL) and disrupts retinoic acid signaling, leading to wide-scale gene expression changes and uncontrolled proliferation of myeloid precursor cells." (PMID 36759620, 2023). "Histone H3.3 is known to localize to nuclear compartments known as promyelocytic leukemia (PML) nuclear bodies, which are frequently mutated and confirmed as oncogenic drivers in acute promyelocytic leukemia." (PMID 38066546, 2023). "Acute Promyelocytic Leukemia is caused by expression of the oncogenic Promyelocytic Leukemia (PML)–Retinoic Acid Receptor Alpha (RARA) fusion protein." (PMID 36880596, 2023). "Our results indicate that PML is a common link between H3.3 mutations in pediatric gliomas and PML-mutated promyelocytic leukemias." (PMID 38066546, 2023). "In an animal model of acute promyelocytic leukemia (APL) the EGCG treatment causes PML/RARα degradation in bone marrow cells." (PMID 37513933, 2023). "Restoration of PML NBs with arsenic or retinoic acid therapies underlies cures of patients with acute promyelocytic leukemia (APL), emphasizing the physio-pathological relevance of these compartments." (PMID 36175410, 2022). "The first link between SUMO and cancer is probably related to the oncogenic fusion of PML protein with the retinoic acid receptor alpha (RARα), which causes acute promyelocytic leukemia (APL), and actively involves SUMO in cell transformation." (PMID 35887358, 2022). "Among them, the detection of co-localization events between telomeres and PML (Promyelocytic Leukaemia) bodies in the so-called ALT-associated PML bodies (APBs) relies on the observation, by confocal fluorescent microscopy, of PML and telomeres." (PMID 35006465, 2021). "The hallmark PML–RARα oncoprotein in acute promyelocytic leukemia is present in patients’ HSCs, indicating an HSC origin." (PMID 34575830, 2021). "As2O3 effects on PML protein and fusion proteins have been investigated in great detail, as these effects underlie its therapeutic effect in the promyelocytic leukemia." (PMID 33946406, 2021).
acute promyelocytic leukemia (continued). "Examples of such “precision medicine” include the BCR-ABL fusion gene in chronic myeloid leukemia (CML), PML-RARA fusions in acute promyelocytic leukemia (APL) and FLT3 mutations in acute myeloid leukemia (AML)." (PMID 34425749, 2021). "Mucin 1‐C and death‐associated protein kinase (DAPK) activate, while promyelocytic leukemia (PML) tumor‐suppressor protein reduces the pyruvate kinase activity of PKM2 via protein–protein interaction." (PMID 33314660, 2021). "Promyelocytic leukemia (PML) bodies are nuclear organelles implicated in intrinsic and innate antiviral defense." (PMID 32365141, 2020). "One of the most investigated involves a translocation between the TRIM19 gene (also known as PML) on chromosome 15 and the retinoic acid receptor alpha (RARα) gene located on chromosome 17, which is associated with acute promyelocytic leukemia." (PMID 32226386, 2020). "Here we show that the histone H3.3 chaperone HIRA (histone cell cycle regulator) associates with promyelocytic leukaemia nuclear bodies (PML-NBs) to stimulate the induction of innate immune defences against herpes simplex virus 1 (HSV-1) infection." (PMID 30901352, 2019). "Acute promyelocytic leukemia (APL) is characterized by PML-RARA translocation, which causes the blockage of promyelocyte differentiation." (PMID 31396278, 2019). "ZnO nanowalls-based electrochemical biosensors have also been used to monitor promyelocytic leukemia and retinoic acid receptor alpha (PML/RARA) fusion genes that can cause acute promyelocytic leukemia (PML)." (PMID 31540160, 2019). "PML was originally identified as a potential gene of interest in tumorigenesis due to its association with acute promyelocytic leukemia (APL)." (PMID 29888200, 2018). "We also demonstrate that the PML retinoic acid receptor-α (PML-RARα) oncofusion protein, which causes acute promyelocytic leukemia, inhibits TNFα induced gene expression and phosphorylation of NF-κB." (PMID 28317833, 2017). "We then determined the effect of Akt inhibition on PML (promyelocytic leukemia) bodies, nuclear structures that are associated with senescence and genotoxic stress." (PMID 26485768, 2015). "CHK2 autophosphorylation seems to also be regulated by PML protein, a tumor suppressor implicated in acute promyelocytic leukemia and a main component of PML-nuclear bodies (PML-NBs), which are nuclear matrix-associated structures." (PMID 25404613, 2014). "Translocations that result in fusion of PML with the retinoic acid receptor α lead to loss of PML bodies, altered transcription, and acute promyelocytic leukemia." (PMID 23555195, 2013). "Promyelocytic leukemia has been implicated in resistance to EMCV since PML−/− MEFs are more sensitive to EMCV than wild-type cells and because specific PML isoforms, PMLIV, and its variant PMLIVa (missing exon 5), protect cells from EMCV infection." (PMID 23734343, 2013). "Within the nucleus, FLASH has variously been reported to be associated with Cajal bodies, PML bodies (Promyelocytic leukemia nuclear bodies) and in histone gene clusters." (PMID 22427918, 2012). "The PML gene was originally identified in acute promyelocytic leukemia (APL), being implicated in numerous cellular functions including oncogenesis, DNA damage, senescence, apoptosis, and protein degradation." (PMID 23316105, 2012). "ATRX has been shown to exhibit a physical interaction with the transcriptional regulatory factor death domain associated protein (DAXX) at promyelocytic leukemia nuclear bodies (PML's) in both human and murine somatic cells." (PMID 20885787, 2010).
acute promyelocytic leukemia (continued). "Several studies have reported that acute promyelocytic leukemia (APL) has a molecular “signature” associated with the presence of the PML-RARα gene fusion, which is distinct from the signatures of AMLs expressing AML1-ETO, CBFβ-SMMHC or C/EBPα mutations." (PMID 19352456, 2009). "We show that the viral EBNA1 protein, previously known to be required to maintain the EBV episomes, also causes the disruption of the cellular PML (promyelocytic leukemia) nuclear bodies (or ND10s)." (PMID 18833293, 2008). "While initially identified as a gene whose rearrangement leads to promyelocytic leukemia, it has since been found that loss of the PML protein is associated with cancer development for a variety of human tumors." (PMID 18833293, 2008). "PML gene was discovered as a fusion partner with retinoic acid receptor (RAR) α in the t(15:17) chromosomal translocation associated with acute promyelocytic leukemia (APL)." (PMID 18509536, 2008). "Similar pathogenic fusion genes are found in leukemias, such as AML1 (acute myeloid leukemia-1)-ETO (eight twenty-one), PML (promyelocytic leukemia)-RARα (retinoic acid receptor alpha), and ETV6 (ETS variant transcription factor 6)-RUNX1 (RUNX family transcription factor 1)." (PMID 40584293, 2025). "GAB2 is likewise overexpressed in many human AMLs with mutations in NPM1 and/or signaling genes, and also in acute promyelocytic leukemia initiated by PML::RARA; the PML::RARA fusion protein may activate GAB2 by directly binding to its 5′ flanking region." (PMID 40773291, 2025). "Given H3.3/ATRX co-localize with PML, and PML-NBs are a known oncogenic driver in acute promyelocytic leukemia, we asked if the H3.3/ATRX mutations might be affecting the PML pathway in pediatric gliomas." (PMID 38066546, 2023). "Similar to PML-mutated acute promyelocytic leukemias, the abnormal PML-NBs can be targeted with arsenic trioxide in H3.3-mutant pediatric gliomas, and this finding could have clinical applications." (PMID 38066546, 2023). "The chromatin remodeling protein alpha thalassemia/mental retardation syndrome X-linked (ATRX) is a component of promyelocytic leukemia nuclear bodies (PML-NBs) and thereby mediates intrinsic immunity against several viruses including human cytomegalovirus (HCMV)." (PMID 35939517, 2022). "Importantly, it was recently shown that cancer-associated chromosomal translocations, for example the PML/RARα translocation in acute promyelocytic leukemia, or the EML4/ALK translocation in lung cancer, give rise to so-called fusion circRNAs (f-circRNAs)." (PMID 31052302, 2019). "HDAC 3 KD in acute promyelocytic leukemia (APL) cells causes restoration of expression of a retinoic acid-dependent gene whose transcription repression was caused by promyelocytic leukemia retinoic acid receptor alpha (PML-RARα)." (PMID 29882797, 2018). "Moreover, in some promyelocytic leukemia cells, PML became fused to retinoic acid receptor α (RARα), abrogating wild-type endogenous PML function and causing neoplastic transformation." (PMID 28725634, 2017). "Interestingly, an analogous reciprocal translocation between the RARA with PML (promyelocytic leukemia) genes has been previously associated with the primary cytogenetic abnormality leading to acute promyelocytic leukemia." (PMID 28851357, 2017). "Due to these important roles, loss of PML-NBs is associated with cancer development or progression in a variety of solid tumours and disruption of PML function through fusion to RARα plays a causative role in promyelocytic leukaemia." (PMID 21305000, 2011). "For example, binding to cysteine residues in the oncoprotein PML-RARα underlies the anticancer activity of arsenic trioxide in individuals with acute promyelocytic leukemia (APL)." (PMID 40717513, 2025). "While acute promyelocytic leukemia (APL) is a well-known subtype with a high risk of DIC due to PML::RARa rearrangements, recent studies have highlighted that non-APL AML also frequently presents with DIC." (PMID 39941313, 2025).